MIR6734 (microRNA 6734)
Synonyms: hsa-mir-6734
Gene: MicroRNA gene on chromosome 1 (43,364,648 to 43,364,715, reverse strand). Ensembl gene ENSG00000283836.
Homologues: Orthologues: chimpanzee MIR6734 (100% identical).